RAD51 (RAD51 recombinase)
Diseases named in the same sentence as RAD51 in open-access papers (continued):
Sharing a sentence is not in itself a finding about the gene and the disease.
tumor (continued). "Retrospective analysis of 15 expansion cohort patients did not demonstrate a correlation between low tumor MGMT expression and patient response, but treatment induced nuclear Rad51 responses in 6 of 12 patients." (PMID 33216844, 2020). "In contrast to other RAD51-based tests, the RECAP test enables the assessment of HR on primary tumor tissue without the need to dissociate tissue and culture tumor cells, greatly reducing the time required to perform the test." (PMID 33003546, 2020). "There continued to be a significant difference in tumor response rate after EC and DOC treatment between Rad51-positive and Rad51-negative EC-induced foci groups for all three criteria." (PMID 20205718, 2010). "Moreover, olaparib-based combination therapy suppressed the formation of Rad51 foci and induced a growth stabilization of BCSphCs and TNBC BRCAmut tumor xenografts, which lacked regrowth after treatment suspension." (PMID 35217791, 2022). "Therefore, the spontaneous RAD51 foci assay would be much more practical than the RECAP assay, as it does not require handling fresh tumor tissue." (PMID 33670893, 2021). "A significantly better tumor reduction and longer PFS was observed in MRE11- and RAD51-negative cases compared with MRE11 or RAD51 positive cases, suggesting that inhibition of these two main HR actors could improve sensitivity to chemotherapy." (PMID 34201502, 2021). "However, when treatment was given after the tumor grew to a certain stage (2 mm in diameter), PARP inhibition was not effective, whereas the effect of RAD51 KD was still significant." (PMID 28359295, 2017). "In addition, when evaluated with a three-dimensional volume reduction using 50% of the PR/SD border, significant differences in the tumor response rate to EC and DOC were observed between Rad51-positive and Rad51-negative baseline foci groups." (PMID 20205718, 2010). "Contingency table analyses demonstrate significant differences in the EC tumor response rate between BRCA1-positive and BRCA1-negative baseline foci groups and between Rad51-positive and Rad51-negative EC-induced foci groups for all three criteria of the response rate (ZIO 65%, ZIO 50%, RECIST)." (PMID 20205718, 2010). "In two different tumor lines with similar, low Trop-2 expression levels, the less SG-sensitive cell line (MDA-MB-231) readily up-regulated Rad51 in response to SG exposure, while the SG-sensitive cell line (SK-MES-1) was defective in HRR, as demonstrated by the lack of Rad51 up-regulation." (PMID 33196706, 2020). "Importantly, however, olaparib-resistant tumours taken 24 hours after their final dose were negative for RAD51 foci, irrespective of tumour phenotype, confirming that despite components of the pathway being up-regulated, the HRR pathway is compromised in these Brca2 knockout tumours, as expected." (PMID 31080552, 2019).
infection (60 papers, 2006 to 2026). The state of being infected such as from the introduction of a foreign agent such as serum, vaccine, antigenic substance or organism. "Infection is associated with a decrease in irradiation-induced 53BP1 and Rad51 foci formation, and in total DNA ligase IV levels." (PMID 32224979, 2020). "We also demonstrate that EnAd infection is associated with inhibition of radiation-induced 53BP1 and Rad51 foci formation and a decrease in total DNA ligase IV levels." (PMID 32224979, 2020). "Labelling of Rad51 identified nuclear speckles forming during BKPyV-infection and co-localisation of Rad51 with the BKPyV LT-Ag." (PMID 35194151, 2022). "We also noted increased expression of RAD51-coding gene in the pre-infection stage in the weakly aggressive isolate." (PMID 33922492, 2021). "Infection with P. syringae led to rapid accumulation of RAD51 2 hours post infection (hpi) for all conditions tested." (PMID 29462140, 2018). "Earlier work in our laboratory implicated the NF-κB signaling pathway and induction of expression of the Rad51 DNA repair protein as key regulators of the transcriptional status of JCV in the early stages of infection." (PMID 28202068, 2017). "Retroviral RAD51 shRNA infection of Aldh2+/+ and Aldh2−/− MEFs led to efficient suppression of RAD51 expression, as assessed by immunoblotting." (PMID 28729482, 2017). "In earlier studies, we demonstrated that infection of primary cultures of microglial cells with HIV-1 leads to an elevated level of Rad51." (PMID 24847939, 2014). "Next, we evaluated the importance of Rad51 in infection of primary culture of human peripheral blood mononuclear cells (PBMCs) by HIV-1." (PMID 24847939, 2014). "It has been demonstrated that efficient productive infection requires RAD51 and, to a lesser extent, FANCD2, suggesting that homologous recombination is important for high-level extrachromosomal replication." (PMID 24260277, 2013). "Lentiviral infection was used to knock down or overexpress RAD51." (PMID 37798649, 2023). "In corroboration with this data, we found that infection of primary cultures of PBMCs with HIV-1 can enhance levels of Rad51, only in those samples with low levels of Rad51 suggesting that activation of Rad51 by HIV-1 relates, in large part, to the basal level of this protein in the cells." (PMID 24847939, 2014). "Since Rad51 stimulates JCV gene expression, the induction of Rad51 expression by DDR following JCV infection may be a positive feedback mechanism whereby viral activity is boosted after infection." (PMID 25310191, 2014). "Besides its role in epimastigotes, TcRad51 is also important during mammalian infection, as shown by increased detection of T. cruzi cells overexpressing RAD51, and decreased detection of single-knockout cells for RAD51, in both fibroblasts and macrophages infected with amastigotes." (PMID 30422982, 2018). "Using this method, we demonstrate that a Cas9-induced DNA double-strand break within the VSG coding sequence can induce RAD51- and BRCA2-dependent VSG recombination with patterns identical to those observed during infection." (PMID 41951731, 2026). "All these observations clearly indicate that Rep hijacks RAD51 and RPA1A to facilitate viral amplification during the infection process." (PMID 37980416, 2023). "The protein levels of NTHL1, MUTYH, FEN1, RAD51, POLD1, and LIG1 were observed to be decreased, during the infection, in a CagA- and phospho-CagA-related manner in both cell lines." (PMID 33339161, 2020). "To investigate the role of Rad51 in JCV infection, we performed transfection/infection experiments with SVGA with JCV and treated cells with and without RI-1." (PMID 25310191, 2014).
infection (continued). "Examination of Rad51 in the uninfected and HIV-1 infected samples demonstrated that while infection of the PBMCs with HIV-1 increased expression of Rad51 in the cells (P≤.05), RI-1 was able to significantly reduce Rad51 levels (P≤.05)." (PMID 24847939, 2014). "Importantly, Rad51 expression is rapidly induced by JCV infection and co-operates with NF-κB to stimulate JCV transcription and providing a positive feedback loop early in infection." (PMID 28202068, 2017).
adenocarcinoma (4 papers, 2014 to 2024). A common cancer characterized by the presence of malignant glandular cells. "HMGA1 activates the RAD51 promoter through two response elements, promoting radiation resistance, while its knockdown sensitizes clear cell adenocarcinoma cells to X‐ray exposure." (PMID 39690136, 2024). "In more advanced adenocarcinomas, however, BRCA2 and RAD51 were overexpressed in about 50% of the cases." (PMID 24641873, 2014). "Surprisingly, although RAD51 was highly overexpressed in the adenocarcinoma tissues, its overexpression was not related with any clinical characteristics." (PMID 27566579, 2016).
movement disorder (3 papers, 2015 to 2017). Neurological conditions resulting in abnormal voluntary or involuntary movement, which may impact the speed, fluency, quality and ease of movement. "Variants in the paralog RAD51, whose protein product interacts with that of RAD51B, have been associated with congenital mirror movement disorders (OMIM 614508) and mirror movement phenotypes are also associated with PD23." (PMID 28117402, 2017).
breast (2 papers, 2017 to 2021). "Here, we analyzed the impact of druggable DDR players in the response of patient-derived colorectal CSCs (CRC-SCs) to CHK1/2 inhibitor prexasertib, identifying RAD51 and MRE11 as sensitizing targets enhancing prexasertib efficacy." (PMID 33921638, 2021).
female reproductive diseases (1 paper, 2024). "The study of RAD51 regulators in female reproductive diseases has novel biomarker potential and implications for therapeutic advancement." (PMID 39359934, 2024).
head and neck tumors (1 paper, 2024). "Another study confirmed that HPV+ head and neck tumors have higher expression of DNA repair genes across all DDR pathways, including higher BRCA1 and Rad51 protein levels than HPV- head and neck tumors." (PMID 38730612, 2024).
hematologic malignancies (1 paper, 2020). "Furthermore, the same RAD51 variant, RAD51C-G135C, also increases the risk for hematologic malignancies [RAD51-G135C, C versus G: OR 1.16 (95% CI 1.02–1.31), dominant model: OR 1.18 (95% CI 1.03–1.36)]." (PMID 33015624, 2020).
reproductive diseases (1 paper, 2024). "Specifically, how the RAD51 regulators intersect reproductive disease etiology is under-studied." (PMID 39359934, 2024).
RAD51 also shares sentences with these, for which no sentence is quoted: bacterial infection (4 papers); genetic disorder (4); chronic lymphocytic leukemia (3); keratoconus (3); rhabdomyosarcoma (3); acne (2); acute leukemia (2); Alzheimer disease (2); astrocytoma (2); autosomal recessive disease (2); bacteremia (2); bone marrow failure syndrome (2); breast and ovarian cancer (2); brucellosis (2); endometrial tumor (2); endothelial corneal dystrophy (2); gastrointestinal stromal tumor (2); Immune Dysfunction (2); Li-Fraumeni syndrome (2); Lynch syndrome (2); mucositis (2); myelodysplastic syndrome (2); Salmonella Infections (2); tuberculosis (2); adrenocortical carcinoma (1); adult T-cell leukemia (1); alcoholic liver diseases (1); asthma (1); atherosclerosis (1); Azoospermia (1).
A further 70 diseases each share a sentence with RAD51 in 1 paper.